PTTG1 (PTTG1 regulator of sister chromatid separation, securin)
Diseases named in the same sentence as PTTG1 in open-access papers (continued):
Sharing a sentence is not in itself a finding about the gene and the disease.
tumor (continued). "The protein levels of DDIT4, TUBA4A, and PTTG1 were markedly elevated in tumor tissues, whereas SLA and BTG2 were notably diminished compared to normal tissues." (PMID 38200058, 2024). "suggesting a correlation between PTTG1 and tumor tissue proliferation and PD-1 therapeutic targets in LUAD patients." (PMID 39144144, 2024). "They identified AQP5, KiSS-1, FZD7, AURKB, UBE2C, and PTTG1 as overexpressed in recurrent CNs, suggesting these genes play a role in tumor progression." (PMID 39066950, 2024). "Many tumor types exhibited increased PTTG1 expression, which is involved in controlling the development and spread of malignancies." (PMID 38200058, 2024). "In HCC, PTTG1 has been shown to promote tumorigenesis by influencing asparagine metabolism, and our experiments have confirmed that PTTG1 can enhance tumor cell proliferation." (PMID 38887516, 2024). "LTB, PTPRC, and PTTG1 were significantly different between normal and tumor samples from TCGA-LUAD, whereas the other model genes were not." (PMID 37671160, 2023). "PTTG1’s contribution to tumor progression is attributed to both its promotion of genetic instability, due to altered sister chromatid segregation during mitosis, and its transcriptional activity on different targets, such as matrix metalloproteinase 2 (MMP-2)." (PMID 38069214, 2023). "The results showed that LTB and PTTG1 genes were significantly up-regulated in tumor tissues, while PTPRC expression was increased in normal tissues." (PMID 37671160, 2023). "In particular, we evaluated the colocalization of these proteins in certain tumor areas that contain different subcellular distributions of PTTG1." (PMID 38069214, 2023). "Given the critical tumor-promoting role of PTTG1 in tumor progression, it is necessary to comprehensively understand its potential in therapy." (PMID 37243239, 2023). "PTTG1 promotes tumor cell proliferation, invasiveness, epithelial–mesenchymal transition, and angiogenesis." (PMID 37243239, 2023). "The role of PTTG1 in tumour microenvironments (TME) was further explored using Single-cell RNA-seq and its prognostic and therapeutic significance was validated in Fudan University Shanghai Cancer Centre (FUSCC) cohort." (PMID 35037540, 2022). "We previously demonstrated that nuclear Pituitary-tumor transforming-gene 1 (PTTG1), overexpressed in several neoplasms, promotes invasiveness through its transcriptional target matrix-metalloproteinase-2 (MMP2)." (PMID 36230799, 2022). "This research is intended to analyze the aberrant expression and clinical significance of PTTG1 in BLCA, explore the relationship between PTTG1 and tumor microenvironment characteristics and predict its potential transcriptional activity in BLCA tissue." (PMID 35768832, 2022). "For instance, PTTG1 expression was distinctly increased in cholangiocarcinoma, and its knockdown suppressed tumor growth via modulating the pathway of MAPK signaling." (PMID 35251171, 2022). "In particular, PTTG1 is one of the 17 gene signatures that can predict metastasis and prognosis in various tumor types." (PMID 35281830, 2022). "This study provides novel insights into the potential role of PTTG1 in tumor formation and prognostic function." (PMID 35281830, 2022). "Some previous experiment-based studies have also indicated that PTTG1 is involved in various tumor processes, such as growth and metastasis, by revealing that PTTG1 overexpression is linked to proliferation and invasiveness." (PMID 35281830, 2022). "Other authors have specifically studied the relationship of PTTG1 upregulation with aggressive tumor behavior, poor prognosis, angiogenesis, and the development of metastasis." (PMID 35805898, 2022).
tumor (continued). "PTTG1 is overexpressed in most human tumors and plays a role in cell replication, DNA damage/repair, organ development, and metabolism, and can accelerate tumor cell proliferation, migration, invasion, and angiogenesis." (PMID 35210406, 2022). "This study also showed that the overexpression of lncRNA PTTG3P induces tumor growth and metastasis in vitro and in vivo, through the modulation of PTTG1/PI3K/AKT signaling." (PMID 36010685, 2022). "We assessed the expression levels of candidate invasion-specific protein biomarkers CTSK, MMP9, MMP2, TIMP2, and PTTG1 by immunohistochemical staining in paraffin-embedded NFPA tumor tissues." (PMID 36052250, 2022). "The pituitary tumor-transforming gene 1 (PTTG1) is a securin and its overexpression has been reported in several neoplasms, frequently those of endocrine origin." (PMID 36230799, 2022). "The current study aimed to design a multi-epitope peptide vaccine targeting main cancer/testis antigens of SP17, AKAP4, and PTTG1, which have a major function in tumor cell proliferation invasion." (PMID 35463817, 2022). "Given the important tumor-promoting role of PTTG1 in a variety of tumors, it is necessary to comprehensively understand the potential of PTTG1 as a potential therapeutic target in different tumors through pan-cancer analysis." (PMID 35281830, 2022). "Using the GEPIA2 tool, the supplementary analysis of PTTG1 expression between tumor and normal tissues depended on the combination of TCGA and GTEx datasets was achieved." (PMID 35281830, 2022). "First, PTTG1 expression in normal tissues, single cells, and various tumor tissues was analyzed based on a consensus database." (PMID 35281830, 2022). "Pituitary tumor-transforming gene-1 (PTTG1), one type of DNA repair-related gene, has been reported to be dysregulated in several tumors and serve as a tumor promotor." (PMID 35251171, 2022). "In the intratubular infiltration areas, nests of cells expressing both OCT4/KLF4 and PTTG1 presence were consistent for a sub-population of tumor stem cells OCT4- and KLF4- positive." (PMID 34209730, 2021). "In different types of cancer, including gastrointestinal tumors, urological tumors, and gynecologic tumors, the upregulation of PTTG1 was related to unfavorable tumor phenotype and adverse prognosis." (PMID 34187556, 2021). "For other genes, AURKA, PTTG1, CDC20, SLC7A5, E2F8, TPX2, and TUBA4A, high expression in the high-risk group was linked to tumour growth and metastasis." (PMID 34131308, 2021). "In the central area of the tumor, PTTG1 staining was more intense in the cytoplasm whereas in the peripheral area, PTTG1 was mostly detected in the nucleus." (PMID 33430117, 2021). "PTTG1 was overexpressed in kidney renal clear cell carcinoma, the higher the grade of tumor cells, the higher the expression is, the poorer prognosis is associated." (PMID 33845847, 2021). "Further studies revealed that inhibiting STAT3 enhanced the inhibitive effect of FAD on HCC cells, whereas overexpressing PTTG1 attenuated the anti-tumor effect of FAD." (PMID 34025420, 2021). "Both simvastatin treatment and PTTG1 knockdown significantly attenuated the expression of c-Myc, FGF-2, and cyclin D3 and increased p21 expression, implicating that simvastatin exerts anti-tumor effects through suppressing PTTG1 function in MDA-MB-231 cells." (PMID 33250768, 2020). "Pituitary tumor transforming gene 1 (PTTG1) is highly expressed in many tumors and regulates tumor growth and progression." (PMID 33490259, 2020). "Transcription factor PTTG1 was seen highly expressed in a variety of tumors and was related to the degree of tumor differentiation, invasion, and metastasis." (PMID 33552118, 2020). "The expression of PTTG1 protein was markedly upregulated in LUAC tissues and was positively associated with the lymphatic invasion of the tumor." (PMID 33490259, 2020).
tumor (continued). "Cytoplasmic and nuclear stain of CCNB1 (n = 246,642 samples) and PTTG1 (n = 243,624 samples) were observed in a low fraction of the tumor cells." (PMID 31801961, 2020). "PTTG1 was seen highly expressed in a variety of tumors and was related to the degree of tumor differentiation, invasion, and metastasis." (PMID 33552118, 2020). "The expression of BUB3, CCNB1, and PTTG1 has been shown to correlate with tumor grade and prognosis in some cancers." (PMID 31801961, 2020). "The fact that reduced expression levels of a mitotic gene lead to tumor appearance is a common issue for many other mitotic regulators such as AurKA, AurKB, PTTG1, and Mad2." (PMID 30862113, 2019). "PTTG1 is highly expressed in a number of tumors to regulate tumor-related metastasis and therapeutic responses." (PMID 31391849, 2019). "Higher growth hormone levels (34.5 ± 7.3 ng/mL vs. 18.4 ± 6.9 ng/mL, p < 0.05), tumor size (13.4 ± 3.6 cm3 vs. 6.3 ± 4.2 cm3, p < 0.05), and tumor recurrence (25.8% vs. 9.7%) were shown in the high-PTTG1 group compared to the low-PTTG1 group." (PMID 31391849, 2019). "Pituitary Tumor Transforming Gene 1 (PTTG1) is upregulated in many types of cancer, and enhances tumor cell growth and metastasis." (PMID 30853662, 2019). "Although the role of PTTG1 in tumor has been extensively studied, the regulation of PTTG1 remains poorly understood." (PMID 30853662, 2019). "In univariate Cox regression analysis, overexpression of PTTG1 (P < .01), large tumor size (P < .01) and advanced TNM stage (P < .01) were significant negative prognostic factors for overall survival in HCC patients." (PMID 31385458, 2019). "PTTG1 is over-expressed in various cancers and promotes tumor development and angiogenesis via triggering the expression of the fibroblast growth factor 2 and VEGF." (PMID 29861465, 2018). "Mice injected with PTTG1 siRNA transfected EC-1 or Eca-109 cells showed a significant delay in tumor development." (PMID 29190924, 2017). "We also observed that miR-146a-3p inhibited the cell cycle progression and tumor growth, and induced senescence in a PTTG1-dependent manner, suggesting p21 was an important target for miR-146a-3p and PTTG1 in BC progression." (PMID 27893422, 2017). "The PTTG1 protein levels were positive correlated with increased tumor size, tumor–node–metastasis (TNM) stage, lymphatic invasion and distant metastasis of BC." (PMID 27893422, 2017). "Xenograft tumor analysis suggested PTTG1 knockdown inhibited tumor growth, and significantly reduced tumor weight." (PMID 27893422, 2017). "mRNA patterns of AKT3 suggest essential connections with tumor growth and metastasis, as well as a strong biomarker potential when used with 3 other genes (PTTG1, MND1, CENPF)." (PMID 29321820, 2017). "PTTG1, an oncogene, is involved in tumor progression, growth, proliferation, and metastasis by regulating several growth factors, such as fibroblast growth factor 2 and vascular endothelial growth factor." (PMID 26900962, 2016). "Taken together, these data suggest a potential role for cyclin B1 and BIRC5 in PTTG1-mediated tumour growth." (PMID 26445238, 2015).
tumor (continued). "For each antigen, we selected patients that tested positive for SP17, AKAP4, and PTTG1 protein expression in tumor cells." (PMID 25739119, 2015). "In this study, we present evidence that PTTG1, behaving as a miR-329, miR-300, miR-381 and miR-655 target gene, acts to mediate cell transformation and tumor formation." (PMID 26320179, 2015). "We generated CTLs from 5 patients displaying SP17, AKAP4 and PTTG1 protein expression and demonstrated specific lysis of autologous tumor cells and CTA-expressing cell lines." (PMID 25739119, 2015). "Our study demonstrated a novel FoxM1-PTTG1 relation and implied a new mechanism of PTTG1 involving tumor progression." (PMID 26264222, 2015). "This study supports a role for increased PTTG1 expression in augmenting tumour development in a subset of MM patients." (PMID 26445238, 2015). "PTTG1 overexpression has been reported to correlate with tumor development in various types of hematopoietic neoplasms." (PMID 23977008, 2013). "The overexpression of PTTG1 has also been demonstrated to promote cell proliferation, tumor metastasis and invasiveness." (PMID 23977008, 2013). "In doxorubicin treated groups, WT tumor weight was reduced to 0.99±0.29 (25% inhibition), PTTG1−/− tumor weight was reduced to 0.1±0.02 g (80% inhibition, p<0.001)." (PMID 21858218, 2011). "As senescence is a determinant of cell responses to anti-neoplastic treatments, these findings suggest PTTG1 as a tumor cell marker to predict anti-neoplastic treatment outcomes." (PMID 21858218, 2011). "Increased PTTG1 expression correlates with higher colorectal tumor grade, invasion of surrounding lymph nodes and increased tumor vascularity." (PMID 21858218, 2011). "PTTG1−/− tumor tissue derived from excised tumors exhibited increased doxorubicin-induced senescence." (PMID 21858218, 2011). "Reports on gliomas, hepatocellular, thyroid and esophageal carcinoma patients also indicate that higher tumor PTTG1 levels correlate with adverse clinical outcomes." (PMID 21858218, 2011). "Head and neck squamous cell carcinomas with higher tumor PTTG1 levels exhibit increased recurrences after radiation, 5-fluorouracil (5-FU) and cisplatinum treatment." (PMID 21858218, 2011). "PTTG1−/− tumors were smaller than WT (1.32±0.39 vs 0.52±0.18 g, p<0.001), confirming results of the tumor volume measurements." (PMID 21858218, 2011). "Taken together, these findings strongly suggest that down regulation of PTTG1 in cancer results in suppression of tumor growth and progression." (PMID 19014669, 2008). "Injection of PTTG1 transfected NIH3T3 cells into athymic nude mice resulted in tumor formation within 3 weeks in all these animals." (PMID 19014669, 2008). "Nude mice injected with A2780 cells expressing PTTG1-siRNA showed a decrease in tumor development and growth." (PMID 19014669, 2008). "We analysed PTTG1 differential expression in PC-3, DU-145 and LNCaP tumor cell lines, cultured in the presence of the methyl-transferase inhibitor 5-Aza-2'-deoxycytidine." (PMID 18426563, 2008). "Growing evidences arise from the literature linking PTTG1 over-expression to both tumor growth and a worse prognosis among independent patient series." (PMID 18426563, 2008). "Nevertheless, no conclusive experiments have been reported to our knowledge explaining the nature of PTTG1 over-expression in tumor samples." (PMID 18426563, 2008). "The overexpression of PTTG1 in tumors correlated with a higher degree of tumor recurrence and tumor aggression." (PMID 19014669, 2008). "Based on these experiments, we suggest that PTTG1 is actively involved in tumor angiogenesis and metastasis via activation of proteolysis and increases in invasion occur through modulation of MMP-2 activity and its expression." (PMID 19014669, 2008). "They observed significantly higher PTTG1 mRNA levels in tumor tissues compared to the corresponding normal tissues." (PMID 19014669, 2008).
tumor (continued). "According to MSP analysis, all tumor samples displayed unmethylated CpG island regardless their PTTG1 status, as well as their respective contra-lateral healthy tissue." (PMID 18426563, 2008). "Using the Cox regression model for multivariate analysis, PTTG-1 expression was a significant predictor for survival next to performance status, tumor stage, LDH and hemoglobin." (PMID 16426442, 2006). "The intensity of PTTG-1 expression as well as the proportion of PTTG-1 positive cells within a tumor was used for univariate and multivariate analysis." (PMID 16426442, 2006). "The transfection of PTTG-1 lead to morphological changes, alterations in growth characteristics of the fibroblasts and tumor formation resulted when injected into nude mice." (PMID 16426442, 2006). "Multivariate analysis using Cox regression confirmed the prognostic relevance of PTTG-1 expression next to performance status and tumor stage in patients with NSCLC." (PMID 16426442, 2006). "In contrast, patients with NSCLC showing strong PTTG-1 tumor expression had a rather unfavourable overall survival which was 5.2 months lower than the group of patients with negative or low PTTG-1 expression." (PMID 16426442, 2006). "The intensity of PTTG-1 staining as well as the proportion of PTTG-1 positive cells within a tumor was taken into consideration for univariate and multivariate survival analyses." (PMID 16426442, 2006). "As a result, only PTTG-1 staining intensity (p = 0.025), tumor stage (p = 0.044) and performance status (p = 0.016) were identified as independent prognostic parameters by the Cox regression model." (PMID 16426442, 2006). "Proportions of PTTG-1 positive tumor cells between 1% and 50%, between 51% and 75% were found in 6 (6.6%) and 15 (16.5%) of all tumors, respectively, only 2 (2.2%) cases were PTTG-1 negative." (PMID 16426442, 2006). "In contrast, the percentage of PTTG-1 positive tumor cells, thrombocyte count, leucocyte count, gender and age were irrelevant with regard to survival time (p > 0.2)." (PMID 16426442, 2006). "The specific mechanisms by which PTTG1 facilitates the invasive behaviors of tumor cells remain obscure, however." (PMID 15649325, 2005). "Three members (PTTG1, PTTG2 and PTTG3) of the PTTG family, which exhibit differential expression in normal and tumor cells have been reported, although only PTTG1 has been studied in detail." (PMID 15649325, 2005). "Results suggest that PTTG1 rs3811999 may influence tumor size or growth pattern, possibly contributing to early tumorigenesis." (PMID 41573212, 2025). "Both genes are implicated in PitNET pathophysiology but act through distinct biological pathways: FGFR4 regulates growth factor signaling, while PTTG1 functions as a proto-oncogene influencing chromosomal stability, cell cycle progression, and tumor proliferation." (PMID 41573212, 2025). "Recent studies indicate that PTTG1 exerts its oncogenic effects through modulation of the NF-κB signaling pathway, with experimental evidence showing that PTTG1 knockdown leads to significant suppression of tumor progression, specifically through inactivation of the NF-κB pathway." (PMID 40072059, 2025). "PTTG1 is widely considered to regulate apoptosis in various neoplasms." (PMID 40072059, 2025). "Furthermore, research has shown that PTTG1 knockout can inhibit the activation of the mTOR signaling pathway through autophagy regulation, suggesting a potential relationship between PTTG1 and autophagy regulation in tumor cells." (PMID 41264123, 2025). "Furthermore, expression levels of PTTG1 correlate to various immune cell types infiltrating tumor niches, including T cells, B cells, neutrophils, and macrophages." (PMID 40072059, 2025). "The results of this study indicate that genetic variation in PTTG1 may influence tumor size or growth pattern, possibly contributing to early tumorigenesis." (PMID 41573212, 2025).